LINC00940 (long independently transcribed non-coding RNA 940)
Gene: Long non-coding RNA gene on chromosome 12 (1,929,202 to 1,936,574, reverse strand). Ensembl gene ENSG00000235049.
Diseases named in the same sentence as LINC00940 in open-access papers:
LINC00940 is named in the same sentence as 2 diseases in open-access papers, as found by Europe PMC text mining. Sharing a sentence is not in itself a finding about the gene and the disease. The quoted sentences say what the papers report.
sarcopenia (1 paper, 2025). Progressive decline in muscle mass due to aging which results in decreased functional capacity of muscles. "MMP24‐AS1, HLA‐DRB6, HLA‐DQA2, DDX42, BAG6, NUSAP1, LINC00940, NME1‐NME2 and AS3MT in the amygdala region showed detrimental effect on all the five sarcopenia‐related traits, whereas HLA‐DRB1, HLA‐DQB1‐AS1 and C6ORF3 showed protective effect (p < 0.05)." (PMID 39535371, 2025). "The over‐expression of nine genes (MMP24‐AS1, HLA‐DRB6, HLA‐DQA2, DDX42, BAG6, NUSAP1, LINC00940, NME1‐NME2 and AS3MT) in the amygdala region showing detrimental effect on all the five sarcopenia‐related traits, whereas three genes (HLA‐DRB1, HLA‐DQB1‐AS1 and C6ORF3) showing protective effect." (PMID 39535371, 2025).
cancer (1 paper, 2023). A tumor composed of atypical neoplastic, often pleomorphic cells that invade other tissues. "We also found a few novel lncRNAs such as LINC00940 and FLJ16779 that have not been reported earlier besides SNHG19, NPBWR1, and lncRNAs that are known to be involved in cancer and other diseases as well." (PMID 37218885, 2023).